IL21 (interleukin 21)
Diseases named in the same sentence as IL21 in open-access papers (continued):
Sharing a sentence is not in itself a finding about the gene and the disease.
chondrosarcoma (1 paper, 2023). A malignant cartilaginous matrix-producing mesenchymal neoplasm arising from the bone and soft tissue. "Since it has been demonstrated that IL-1 inhibits STAT3’s chromatin accessibility in a chondrosarcoma cell line, IL-21 may reverse this inhibition and induce the proliferation of IL-1-stimulated Vγ4+nγδT17 cells but not Vγ6+nγδT17 cells." (PMID 37662923, 2023).
chronic myeloid leukemia (1 paper, 2023). "Also, feeder cells, such as the chronic myeloid leukemia-derived cell line (K562), in combination with cytokines or expression of membrane-bound IL-15, IL-21, or 4-1BB are often used to enhance NK cell proliferation." (PMID 36762286, 2023).
colon adenocarcinoma (1 paper, 2023). "To determine the IL21-producing cells in mouse tumors, we analyzed public scRNA-seq data of CD4+ T cells in the MC38 colon adenocarcinoma model." (PMID 37546701, 2023).
Constipation (1 paper, 2021). Infrequent or difficult evacuation of feces. "We found the reduced levels of TGF-β, IL-10, and IL-21, and the increased levels of GM-CSF, IL-17A, IL-17F, IL-22, and IL-23 in the serum of constipation EAE mice." (PMID 34301274, 2021). "We found that the concentrations of TGF-β, IL-10, and IL-21 were decreased while the levels of GM-CSF, IL-17A, IL-17F, IL-22, and IL-23 were increased in constipation EAE mice and FMT EAE mice compared to EAE mice." (PMID 34301274, 2021). "Moreover, the serum levels of TGF-β, IL-10, and IL-21 were decreased while the GM-CSF, IL-17A, IL-17F, IL-22, and IL-23 were increased in the constipation EAE mice." (PMID 34301274, 2021).
contact dermatitis (1 paper, 2016). An inflammatory skin condition caused by direct contact between the skin and either an irritating substance or an allergen. "Previously, we have shown that mice with a T cell-specific overexpression of CREMα show an enhanced IL-21 production both in vitro after T cell stimulation with anti-CD3 and anti-CD28 and in vivo in a contact dermatitis model." (PMID 28066428, 2016).
cryoglobulinemia (1 paper, 2014). Cryoglobulinemia is a type of vasculitis that is caused by abnormal proteins (antibodies) in the blood called 'cryoglobulins.' At cold temperatures, these proteins become solid or gel-like, which can block blood vessels and cause a variety of health problems. "Moreover, these double-high patients had significantly higher positivity of anti-nuclear antibody, cryoglobulinemia, and lymphotropic HCV and higher amounts of IL1-β, IL21, IL23." (PMID 24905921, 2014).
delirium (1 paper, 2025). A disorder characterized by confusion; inattentiveness; disorientation; illusions; hallucinations; agitation; and in some instances autonomic nervous system overactivity. "We identified several soluble factors and immune cell types linked to delirium, including IL-1α, IL-22, IL-21, CCL11, CXCL1, CXCL13, and VEGF-A, as well as exhausted B cells and activated T cells." (PMID 41219650, 2025). "Overall, delirium was correlated with several cytokines (decreased IL-22, IL-21, IL-1α), chemokines (increased CXCL1, CCL11, CXCL13), and growth factors (increased HGF, and a tendency towards increased VEGF-A)." (PMID 41219650, 2025).
demyelinating disease (1 paper, 2025). A broad group of disorders that affect the myelin sheaths that cover the neurons. "Conversely, the inhibitory roles of IL-3 and IL-21 highlight their contribution to the inflammatory milieu, further linking glial-peripheral immune crosstalk to the progression of demyelinating diseases." (PMID 40399986, 2025).
dermatitis (1 paper, 2023). An inflammatory process affecting the skin. "All mice with oxazolone-induced dermatitis had a dramatic increase in IL-1β, IL-4, IL-6, IL-10, TNF-α, IFN-γ, IL-16, IL-17C, IL-17E, IL-17F, IL-21, IL-22, and MIP-3a, whereas the concentrations of IL-12p70, IL-2, IL-17A, and IL-23 were lower in dermatitis mice." (PMID 37889696, 2023).
diabetic retinopathy (1 paper, 2020). "Collectively, these data demonstrated that Tfh cells produced IL-21 cytokine, as well as other pro-inflammatory and pro-angiogenic cytokines in diabetic retinopathy and retinal neovascularization in vivo." (PMID 32226551, 2020).
disc degeneration (1 paper, 2020). "Chen proposed that interleukin-21 played a role in the pathological process of disc degeneration and could aggravate disc degeneration by stimulating TNF-α through the JAK/STAT pathway." (PMID 32111963, 2020).
endometrial cancer (1 paper, 2020). Primary or metastatic malignant neoplasm involving the endometrium (mucous membrane that lines the endometrial cavity). "A third smaller, but distinctly separate, network of IL13, IL21, ANKAR, CAPS, and IGFALS was associated with Wnt and VEGF signaling, and are likely associated with environmental cues in high-grade endometrial cancer." (PMID 32471032, 2020). "Activated CD8+ TIL in endometrial cancer barely produced IL-13 (1.06%), but they did produce GM-CSF (median 26.08%) and, to a lesser extent, IL-21 (median 8.79%) and very little IL-10 (median 3.7%)." (PMID 32471032, 2020).
endotoxemia (1 paper, 2016). "In accordance, VDR KO mice have shown to be more susceptible to LPS-induced endotoxemia, have higher expressions of inflammatory cytokines (e.g., TNF-α, IL-1a, IL-1β, IL-10, IL-21, and IFN-γ), and experience more weight loss, bleeding, ulceration, septic shock, and death compared to wild-type mice." (PMID 28066436, 2016).
enteritis (1 paper, 2023). Inflammation of the small intestine. "It is likely that a high abundance of IL-21 in the gills and intestine could be beneficial to the body to control excessive inflammation during enteritis caused by A. hydrophila." (PMID 37759501, 2023). "In our previous study, we showed that A. hydrophila infection resulted in mild enteritis in grass carp and that IL-21+ and CD3γ/δ+ cells are present in the intestine." (PMID 37759501, 2023). "Here, we sought to determine whether IL-21 is produced by CD3γ/δ cells and, if so, whether the IL-21 producing CD3γ/δ cells are involved in enteritis." (PMID 37759501, 2023).
esophageal cancer (1 paper, 2026). A primary or metastatic malignant neoplasm involving the esophagus. "Post-neoadjuvant radiotherapy samples from patients with esophageal cancer showed a positive correlation between IL-21 levels and CD8+ T cell infiltration." (PMID 41505202, 2026).
gastric adenocarcinoma (1 paper, 2023). "The human gastric adenocarcinoma cell line AGS responded to IL-21 by increasing the production of MMP-2 and MMP-9 in a NF-kB-dependent fashion and treatment of H. pylori-infected gastric explants with an antibody against IL-21 decreased the production of epithelial cell-derived MMP-2 and MMP-9." (PMID 36769214, 2023).
genital herpes (1 paper, 2013). Herpes simplex infection of the genitals, most commonly caused by the herpes simplex-2 virus. "As the IL-21R expression was increased in vaginal tissue early after HSV-2 infection and disease was more severe in IL-21R KO mice than in WT we concluded that the IL-21 - IL-21R network is important in the innate response to genital herpes in mice." (PMID 24358128, 2013).
granulomatosis with polyangiitis (1 paper, 2013). A small-vessel necrotizing vasculitis characterized by the association of inflammation of the vessel wall and peri- and extravascular granulomatosis. "The present study aimed to explore a possible role for IL-21 producing Th-cells in the immunopathogenesis of granulomatosis with polyangiitis (GPA)." (PMID 23799890, 2013).
hemorrhagic fever (1 paper, 2013). An infectious disease caused by certain viruses or bacteria that can damage the walls of tiny blood vessels, making them leak, and can hamper the blood's ability to clot and cause severe, life-threatening illness. "Upregulation of IL21 was previously noted in a LCMV model of hemorrhagic fever and recent studies have provided genetic evidence that the IL21 gene is important for successful responses to LASV exposure, suggesting that further analysis of the importance of IL21 in LASV exposure is warranted." (PMID 23638192, 2013).
hemorrhagic fever with renal syndrome (1 paper, 2017). A viral infectious disease that is a hemorrhagic fever, located_in kidney, has_material_basis_in Hantaan virus, has_material_basis_in Dobrava-Belgrade virus, has_material_basis_in Seoul virus, or has_material_basis_in Puumala virus, which are carried and transmitted_by rodents. "One study shows a high overexpression of IL-21 in patients with hemorrhagic fever with renal syndrome (HFRS) caused by hantavirus." (PMID 28708900, 2017).
herpes zoster (1 paper, 2016). A common dermal and neurologic disorder caused by reactivation of the varicella-zoster virus that has remained dormant within dorsal root ganglia, often for decades, after the patient's initial exposure to the virus in the form of varicella (chickenpox). "In patients with herpes zoster, the serum level of IL-17, IL-23, IL-21, IL-4 and IL-12 as well as VZV IgG antibodies titer were statistically significantly increased compared to control group." (PMID 26934574, 2016). "In the present study we investigated the serum cytokine profile (IL-17, IL-23, IL-21, IL-4, IL-12), representing cellular and humoral immunity and assessed the level of VZV IgG antibodies in patients with herpes zoster." (PMID 26934574, 2016). "We investigated the serum concentrations of IL-17, IL-23, IL-21, IL-4, IL-12 and the level of VZV IgG antibodies in 23 patients with herpes zoster who did not develop superinfection." (PMID 26934574, 2016).
hookworm infection (1 paper, 2022). "In addition, decreased IL-18 and RANTES were detected in women with only hookworm infection compared to uninfected women, whereas IL-21 and SDF-1α were increased." (PMID 36330509, 2022).
Hyperinsulinemia (1 paper, 2017). An increased concentration of insulin in the blood. "To simulate the effect of hyperinsulinemia we extended the previous network to add the regulation of IL-10 by insulin via the AKT pathway; and the STAT3-signaling cytokines: IL-10, IL-6, and IL-21 all use STAT3." (PMID 28651594, 2017).
idiopathic pulmonary arterial hypertension (1 paper, 2025). A sporadic form of pulmonary arterial hypertension (PAH) characterized by elevated pulmonary arterial resistance leading to right heart failure. "IL-21 also fosters M2 polarization in primary alveolar macrophages, and following lung transplantation, elevated levels of IL-21 and M2 phenotype markers have been detected in patients with idiopathic pulmonary arterial hypertension." (PMID 40376002, 2025).
Interstitial pneumonitis (1 paper, 2021). "Furthermore, lymphocytes, neutrophils, and monocytes act dynamically to produce immune-mediated interstitial pneumonitis, with inflammation and activation of subsequent cytokines, such as IL-1, IL-6, IL-8, IL-21, TNF-β, and MCP-1, at the site of infection." (PMID 34451520, 2021).
intervertebral disc degeneration (1 paper, 2020). "Likewise, a recent study showed that IL-21 played a role in the pathological development of intervertebral disc degeneration and it may worsen intervertebral disc degeneration by inducing TNF-α." (PMID 33014656, 2020).
invasive breast carcinoma (1 paper, 2025). A carcinoma that infiltrates the breast parenchyma. "Similar to IL-21, our results showed changes in the IL-22 levels in patients with invasive breast cancer." (PMID 40729006, 2025). "The results showed changes in the IL-21 levels in patients with invasive breast cancer." (PMID 40729006, 2025). "The IL-21 serum concentrations in patients with invasive breast cancer have not yet been analysed, taking into account both molecular subtypes and degree of malignancy." (PMID 40729006, 2025). "This preliminary study did not reveal statistically significant differences in serum IL-21 and IL-22 levels between patients with invasive breast cancer and those with benign breast lesions." (PMID 40729006, 2025).
juvenile dermatomyositis (1 paper, 2020). Juvenile dermatomyositis (JDM) is the early-onset form of dermatomyositis (DM), a systemic, autoimmune inflammatory muscle disorder, characterized by proximal muscle weakness, evocative skin lesion, and systemic manifestations. "While one could anticipate that all cTfh subsets participate similarly in promoting antibody production, cTfh17 cells, but not cTfh2 cells, secreted IL‐21 in patients with juvenile dermatomyositis." (PMID 33230950, 2020).
kidney transplant (1 paper, 2020). A surgical procedure in which one or both kidneys from a donor are implanted into a recipient. "In contrast, exogenous administration of IL-21 accelerated acute rejection in a comparative translational kidney transplant (KT) mouse model." (PMID 32991326, 2020).
latent infection (1 paper, 2017). "Therefore, in a T. gondii model of chronic infection, Tfh appear to be the primary source of IL-21 and exhaustion of these cells compromises CD8 T cell functionality leading to reactivation of the latent infection." (PMID 29163509, 2017).
leishmaniasis (1 paper, 2020). Infectious disease that is transmitted through the bite of hematophagous female phlebotomine sand flies. "Altogether, the contribution of IL-21/IL-21R to leishmaniasis remains a conundrum with limited studies on gene-deficient and receptor-deficient experiments to validate a distinct role." (PMID 33415318, 2020). "In line with this, evidence suggests that IL-21/IL-21R signalling regulates antibody isotype switching especially IgG subclasses, IgG1 and IgA, the former associated with progression of leishmaniasis." (PMID 33415318, 2020).
liver cirrhosis (1 paper, 2021). "Th17 cells are increased in liver cirrhosis and are probably the source of increased serum IL-21 levels." (PMID 34502427, 2021). "In contrast, IL-21 is also expected to exacerbate liver cirrhosis due to HBV infection." (PMID 34502427, 2021). "Increased IL-21 may activate HSCs and exacerbate liver cirrhosis." (PMID 34502427, 2021).
lymph node metastasis (1 paper, 2024). "The therapeutic effect of IL-21 was further validated in vivo with a spontaneous lymph node metastasis model, which is more clinically relevant." (PMID 38559676, 2024). "Therefore, local administration of IL-21 could be a promising procedure to target lymph node metastasis." (PMID 38559676, 2024).
lymphocytic leukaemia (1 paper, 2012). "BIM up-regulation was already shown to be mediated by STAT1 in IL-21-treated lymphocytic leukaemia cells and TNF-α+IFN-γ-exposed β-cells, while CHOP activity is required for BIM up-regulation and apoptosis induction in thapsigargin-treated thymocytes and growth factor-deprived lymphoid precursors." (PMID 22347430, 2012).
Lymphoproliferative Disorders (1 paper, 2015). "IL-21 may act as a paracrine growth factor in other lymphoproliferative disorders." (PMID 25961061, 2015).
measles (1 paper, 2021). A highly contagious viral infection caused by the measles virus. "T helper (Th) cells expressing IL21 (1–10%), TGFB1 (2.9–9.5%), and IL21 plus TGFB1 (0.3–3.5%) were as frequent among the SARS-CoV-2-reactive Th cells as among measles-reactive Th cells of a healthy control (2%, 6%, 0.6%)." (PMID 33785765, 2021).
membranous nephropathy (1 paper, 2018). "Significantly higher frequency of CD4+/CXCR5+, CD4+/CXCR5+/ICOS+ and CD4+/CXCR5+/PD-1+ TFH cells, and higher serum levels of IL-17A, IFN-γ, IL-2, IL-10, IL-4 and IL-21 were detected in hepatitis B virus-associated membranous nephropathy patients compared to the healthy controls." (PMID 28770269, 2018).
metastatic cancer (1 paper, 2024). A carcinoma which has spread from the original site of growth to another anatomic site. "Our findings provide support for further clinical investigation into a triple combination therapy involving MWA, IL-21, and ICIs for the treatment of metastatic cancer." (PMID 38833177, 2024).
mononucleosis (1 paper, 2017). "The Epstein-Barr Virus, the most common cause of mononucleosis, does infect B cells directly and some literature reports a delay in IL-21 production during Epstein-Barr Viral infection." (PMID 28427414, 2017). "In this study, IL-21 was elevated compared to a control group of children with prolonged fevers thought to be due to mononucleosis." (PMID 28427414, 2017). "The prior study showing specific IL-21 elevation in KD in the Korean cohort was notable in that it included only suspected mononucleosis subjects in the control group." (PMID 28427414, 2017). "In light of our current results, it is reasonable to consider that the original study may be more significant for a lack of IL-21 elevation during evaluation for mononucleosis rather than for a specific elevation associated with KD." (PMID 28427414, 2017).
nephritis (1 paper, 2019). Inflammation of renal tissue. "Intravenous injection of Baicalin-induced Foxp3+ regulatory T cells could relieve nephritis, inhibit Tfh cell differentiation and IL-21 production." (PMID 30760702, 2019).
neuropathy (1 paper, 2024). A disorder affecting the nervous system that manifests with pain, tingling, numbness, and/or muscle weakness. "Genetic IL-21R deficiency completely protected against neuropathy development, demonstrating that IL-21 signaling was required for autoimmune pathogenesis." (PMID 39087473, 2024). "Additionally, we demonstrate that IL-21 signaling was required for neuropathy development and that IL-21 upregulated CXCR6, a chemokine that promotes CD4+ T cell localization within peripheral nerves." (PMID 39087473, 2024). "Thus, it is possible that IL-21 signaling on DCs and macrophages may also play a role in promoting neuropathy." (PMID 39087473, 2024). "Moreover, CD4 and IL-21 staining was absent in the non-neuropathic controls (NOD.WT), which suggests that the neuropathy was associated with increased IL-2–producing CD4+ T cells in peripheral nerves." (PMID 39087473, 2024).
Opportunistic infection (1 paper, 2018). An infection that is caused by a pathogen that would generally not be able to cause an infection in a host with a normal immune system. "Additionally, activation of the IL-21/IL-21 receptor (IL-21R) pathway in T cells facilitates better control of human immunodeficiency virus (HIV) replication, while children with IL-21R deficiency are predisposed to opportunistic infections due to impaired cellular immunity." (PMID 29854291, 2018).
osteonecrosis (1 paper, 2022). A none disease characterized by death of bone tissue due to a lack of blood supply. "Moreover, high levels of inflammatory factors such as IL-6 and IL-21 could also aggravate the symptom of osteonecrosis." (PMID 35035862, 2022).
osteoporosis (1 paper, 2024). A condition of reduced bone mass, with decreased cortical thickness and a decrease in the number and size of the trabeculae of cancellous bone (but normal chemical composition), resulting in increased fracture incidence. "However, IL21’s role in osteoporosis linked to shoulder joint degeneration remains unreported." (PMID 38728237, 2024).
Parkinson disease (1 paper, 2021). A progressive degenerative disorder of the central nervous system characterized by loss of dopamine producing neurons in the substantia nigra and the presence of Lewy bodies in the substantia nigra and locus coeruleus. "From the list of proteins taking part in inflammation, IL-21, IL-22, IL-1B are important proteins that are involved in MS, Parkinson’s disease, and other viral-bacterial CNS infections." (PMID 33833673, 2021).
pneumonia (1 paper, 2015). An acute, acute and chronic, or chronic inflammation focally or diffusely affecting the lung parenchyma, caused by an infection in one or both of the lungs (by bacteria, viruses, fungi, or mycoplasma.). "Moreover, STAT3-dependent IL-1β expression in cDCs at least partially explains the IL-21-mediated pathologic response occurring during infection with pneumonia virus of mice." (PMID 26269257, 2015).